IL6 (interleukin 6)
Diseases named in the same sentence as IL6 in open-access papers (continued):
Sharing a sentence is not in itself a finding about the gene and the disease.
Obesity (continued). "Additionally, dopamine and glutamate were positively correlated with neuroinflammatory cytokines (IL-12 and IL-6), leptin and BMI as markers of obesity, and cholesterol as an atherogenic marker." (PMID 33312720, 2020). "A murine study from 2018 showed that IL-6 treatment enhances AKT signaling and reduces gluconeogenic gene expression in livers from low and high fat fed mice, demonstrating that the beneficial effects of IL-6 on glucose and insulin homeostasis, in vivo, are maintained in obesity." (PMID 32393961, 2020). "IL-6 is a proinflammatory cytokine involved in obesity and insulin resistance." (PMID 33133214, 2020). "In the presence of obesity, sepsis resulted in increased IL-1β and IL-6 levels in PLF." (PMID 33223959, 2020). "In fact, high levels of IL-6 suppress hepatocyte proliferation in obesity, maybe as a protective mechanism." (PMID 32210914, 2020). "We hypothesized that blocking IL-6 trans-signaling with sgp130Fc in the brain would impact AD and/or obesity progression." (PMID 32630818, 2020). "Obesity, as a characteristic of metabolic syndrome, is related to chronic low-grade inflammation in obese subjects, because of various pro- and anti-inflammatory cytokines produced by adipose tissues, including IL-6, TNF-α, CCL2, PAI-1, and others." (PMID 32486076, 2020). "It was postulated that the higher interleukin-6 frequently observed in obesity could be behind the higher DBP concentrations among obese individuals." (PMID 33014456, 2020). "Leptin may upregulate the production of inflammatory cytokines such as CRP, TNF-α, IL-6, and IL-12 and be involved in low-grade inflammation, which plays a central role in the pathophysiology of obesity, depression, metabolic and cardiovascular disease." (PMID 33036196, 2020). "Further, NF-κB is a critical transcription factor of M1 macrophages, regulating the expression of a variety of inflammatory genes, including those encoding IL-6, IL-1β, MCP-1, and cyclooxygenase-2 (COX-2), shown to play important roles in obesity-related PDAC promotion." (PMID 31277269, 2019). "This requires confirmation because of the key significance of the myostatin/IL-6 balance in the fat infiltration/apoptosis/failure of injury repair occurring in obesity and diabetes where stem cell damage may be a key." (PMID 31430893, 2019). "To further investigate this subset of mice, we tested for differences within various parameters associated with diet-induced obesity between the subsets of mice with or without detectable IL-6." (PMID 31262998, 2019). "Our study found that IL-6 level was significantly elevated in adolescents with obesity." (PMID 31120986, 2019). "Obesity is a chronic low-grade inflammation process; thus the cytokines and other inflammatory markers produced by over-loading adipose tissue, such as interleukin-1 (IL-1), IL-6, and tumor necrosis factor alpha (TNF-alpha), will be increased." (PMID 31681268, 2019). "Interestingly, IL-10 in obese mice, displayed significant anti-obesity and anti-inflammatory effects, such as reduced serum total cholesterol, adipocyte size, proinflammatory cytokine secretion IL-6 in adipose tissue." (PMID 31261958, 2019). "Finally, the involvement of IL-6 cytokine family members in kidney disease will be presented in the context of three regularly overlapping conditions: obesity, hypertension and diabetes." (PMID 30871285, 2019). "We and other reported the increased expression of IL-6/IL-6R in the adipose tissue in obesity." (PMID 31718015, 2019). "Cytokines, interleukin 6 (IL-6) and tumor necrosis factor alpha (TNF-α), which regulate the production of high-sensitivity C-reactive protein (hsCRP) correspondingly are linked to high blood pressure and obesity." (PMID 31671730, 2019).
Obesity (continued). "Previous studies have shown that as obesity increases, skeletal muscle loss leads to an increase in inflammatory adipocytes, such as leptin, tumor necrosis factor alpha (TNF-α), and interleukin (IL-6), and reduces concentrations of adiponectin or IL-15." (PMID 31269909, 2019). "Interestingly, the results of this meta-analysis suggested that polymorphisms in the adipokine genes, ADIPOQ, IL-1β, IL-6, and TNF-α, increase the risk of obesity." (PMID 31354816, 2019). "Moreover, a direct relationship has been observed between IL6 in fatty tissue and insulin resistance in human obesity." (PMID 31649930, 2019). "IL-6 signaling plays an important role in alternative activation and recruitment of macrophages and metabolic homeostasis; this cytokine is constantly produced in obesity." (PMID 31191541, 2019). "Furthermore, elevated concentrations of IL-6, TNF-α, IL-10, and IFN-γ were associated with overweight and obesity (BMI above 25)." (PMID 31139232, 2019). "For example, plasma concentrations of the n-6 PUFA GLA were positively associated with breastmilk IL-6 among women without overweight or obesity." (PMID 31141526, 2019). "However, adipose tissue and muscle also act as endocrine organs that release various cytokines, such as leptin, adiponectin, tumor necrosis factor-alpha, and interleukin-6, and alter insulin sensitivity in obesity and metabolic syndrome." (PMID 31470507, 2019). "The different patterns and roles of IL-6 in obesity and following exercise may be masking any potential effects, wherein IL-6 is downregulated by weight loss but upregulated by skeletal muscle contractile activity." (PMID 31590286, 2019). "Inflammatory cytokines appear to play a key role in linking obesity and colorectal carcinogenesis particularly so for IL-6 and tumor necrosis factor-α; a recent study also describing IL-13 as a potential factor involved in the development of obesity-related colon cancer onset." (PMID 31906216, 2019). "Moreover, our previous findings had shown distinct changes in the methylation profile of inflammatory genes after different obesity treatments, with reduction in the IL-6 methylation level six months after RYGB." (PMID 31133015, 2019). "In addition, vitamin D acts as an immune-suppressor of inflammatory markers, including tumor necrosis factor-alfa (TNF-α) and interleukin (IL)-6, both of which are characteristically elevated in subjects with obesity." (PMID 31362440, 2019). "Obesity is associated with increased expression of adipokines including TNF-α, IL-6, and CCL2 which can cause damage to adipocytes and the release of FFAs, and the combined effect of TNF-α and FFAs may trigger further IL-8 production." (PMID 31443599, 2019). "Moreover, the level of interleukin-6 was strong correlated with BMI which is the general accepted method used for the assessment of the obesity or overweight degree." (PMID 30605486, 2019). "The child with the highest degree of obesity from the group (>99th percentile) presented the highest salivary level of IL-6 (98 ng/mL), followed by two children (96th and 98th percentiles) with a IL-6 level of 61.2ng/mL." (PMID 30605486, 2019). "These included changes in 5 immune function-related proteins, among which IL-6 and Ccl3 both decreased by exercise and correlated with obesity and insulin-sensitivity in our mice, likely due to increased and suppressed inflammation by HFD and exercise, respectively." (PMID 31019501, 2019). "In conclusion, the results of this study suggest that visfatin and IL-6 levels might play a role in the pathogenesis of obesity and periodontal disease and that these can be used as reliable markers for monitoring the progress of both diseases." (PMID 31365708, 2019). "Hypertrophic or apoptotic adipocytes in individuals with obesity increased the pro-inflammatory status, due to the secretion of several molecules such as leptin, resistin, interleukin 6 (IL-6) and tumor necrosis factor-α (TNF-α) that can activate M1 macro-phage-response." (PMID 31118060, 2019).
Obesity (continued). "Obesity-associated hyperplasia and hypertrophy of adipose tissue cause an increase in proinflammatory cytokines, such as tumor necrosis factor alpha (TNF-α) and interleukin-6 (IL-6)." (PMID 31450844, 2019). "We observed increased gene expression of Gr1, Il6, and Il10 in the adipose of obese mice, suggesting an obesity-induced expansion in myeloid markers and cytokines that may promote the accumulation of immunosuppressive MDSCs." (PMID 31835454, 2019). "Obesity-related genes were retrieved in the Digsee database and the top 15 obesity-related genes were selected as disease genes (Adipoq, Igf1, Fto, Hsd11b1, Tnf, Gh1, Mc4r, Lep, Pparg, Il6, Crp, Lepr, Pomc, Lpl, and Ghr1)." (PMID 31060494, 2019). "The increase in obesity showed a direct effect on IL-6 (males 0.36, 95% CI 0.28, 0.43; females 0.58, 95% CI 0.51, 0.64) and CRP (males 0.76, 95% CI 0.62, 0.90; females 1.00, 95% CI 0.86, 1.13) and an inverse relationship with adiponectin in females (-2.43 95% CI -4.37, -0.50)." (PMID 31071114, 2019). "Moreover, IL-6 is responsible for macrophage recruitment to adipose tissue in obesity, leading to the development of inflammation, insulin resistance, and T2D." (PMID 31736870, 2019). "Obesity increases IL-6 production, which in turn regulates the tumor microenvironment of colitis-associated colorectal cancer by shifting intestinal macrophage polarization to the tissue regenerating M2-like macrophages that functionally overlap with tumor-associated macrophages in mouse models." (PMID 31379820, 2019). "Likewise, IL-6 has been suggested to be involved in the development of obesity-related and T2D-related IR (Fève and Bastard, 2009)." (PMID 32063863, 2019). "Additionally, metabolic changes caused by obesity alter critical hematopoietic and immunologic pathways, such as TNF-α, IL-1, IL-6, and PGE2, which also have pro-tumorigenic potential." (PMID 31616626, 2019). "In addition, while higher hepcidin concentration is expected in obesity due to increased inflammation and IL-6 concentration, the observed difference in this study between the normal weight and overweight/obese groups was not statically significant." (PMID 31597392, 2019). "It is important to consider that a detrimental role of IL-6 exists and that obesity particularly increases IL-6 levels both in humans and mice due to macrophage secretion in the adipose tissue, promoting a low-grade systemic inflammation that can impair insulin signaling and glucose metabolism." (PMID 30875990, 2019). "The expression and secretion of MCP-1, IL-6, and resistin are increased in obesity, playing an important role in the appearance of the inflammatory M1 type macrophages, and decreasing the expression and production of the protective adiponectin and IL-10 in the adipose tissue." (PMID 31438590, 2019). "However, in case of obesity the secreted adipokines take on a more proinflammatory profile, secreting IL-6, TNFα and leptin, as well as resistin and visfatin." (PMID 30787925, 2019). "Our findings lead us to speculate that targeting IL-6 and CCL-2 is a possible therapeutic strategy for inhibition of obesity-associated CNS inflammation." (PMID 31507583, 2019). "Furthermore, IL-6 stimulates polarization and proliferation of M2 macrophages via induction of IL-4R expression as shown in mouse models of obesity." (PMID 31694340, 2019). "In obesity, macrophages and immune system cells invade the adipose tissue in response to fat accumulation leading to the production of proinflammatory cytokines including interleukin 6 (IL-6)." (PMID 31597392, 2019). "While sudden and acute induction of the IL-6 cascade promotes muscle growth, IL-6 sustained and elevated release and STAT3 activation have been associated with muscle atrophy occurrence in several catabolic conditions, such as obesity, diabetes, and age-induced sarcopenia or cancer." (PMID 31114509, 2019).
Obesity (continued). "By contrast, obesity alters iron homeostasis as a consequence of excess adipose tissue, which triggers a low grade chronic inflammation involving cytokines such as interleukin 6 (IL-6) and leptin." (PMID 30909605, 2019). "Indeed, increased IL-6 levels in response to obesity or physical exercise promotes the secretion of the incretin hormone GLP-1 by intestinal L-cells and pancreatic α-cells leading to increased insulin secretion." (PMID 30989320, 2019). "Moreover, even after adjusting for age, sex, ethnicity, glucose tolerance, and the degree of obesity, IL-6 remained a significant predictor of prandial adipose IR." (PMID 30637483, 2019). "Similarly, in a study performed on Caucasian children, the IL-6572CC, IL-6 190 CC, and IL-6 174 CG genotypes were encountered more frequently in children with obesity, whereas the IL-6 174 CC genotype was found to be a protective factor for childhood obesity." (PMID 30338250, 2018). "In addition, the proinflammatory cytokine interleukin (IL)-6 from adipose tissue also contributes to obesity-induced insulin resistance in both humans and mice." (PMID 30459770, 2018). "In addition, IL-6 has recently been proposed to play a central role in the link between obesity, inflammation and coronary heart disease." (PMID 29466985, 2018). "During obesity-associated hepatocellular carcinoma (HCC) development, expression of interleukin-6 (IL-6), which results from a chronic low-grade proinflammatory state in white adipose tissue and liver, helps to stabilize Mcl-1 via promotion of GSK3β inactivation and suppression of HUWE1." (PMID 30176860, 2018). "These evidences suggest that ARID1A may affect obesity through cytokines (IL6), adipokines (leptins) or lipids mediated lipid pathways." (PMID 29500370, 2018). "Markers of inflammation, such as tumor necrosis factor alpha (TNF-α), interleukin-6 (IL-6), CRP and MCP-1, are increased in peripheral blood levels in obesity and are associated with IR and may predict the development of type 2 diabetes." (PMID 29694633, 2018). "As in the case of IL6, elevated circulating IL18 serum levels were found in obese and T2DM patients, reduced after weight loss and were postulated as risk predictors for metabolic syndrome development before detection of obesity and IR." (PMID 30158466, 2018). "However, numerous studies have shown that IL-6 levels are greatly elevated in obese humans and correlate positively with obesity and waist circumference." (PMID 29396550, 2018). "Obesity increases systemic levels of tumor necrosis factor α (TNFα) and interleukin-6 (IL-6)." (PMID 30591653, 2018). "Interestingly, such IL-6 transsignalling prevents obesity-induced recruitment of macrophages into adipose tissue that paradoxically failed to improve systemic insulin sensitivity." (PMID 29695802, 2018). "Nevertheless, a recent study suggests that IL-6 regulates M2 differentiation in ATM in obesity." (PMID 29765984, 2018). "We now know that diseases that fall into the metabolic syndrome spectrum, such as T2DM and obesity, are associated with dysfunctional immunity and low low-grade inflammation, as shown by increased levels of proinflammatory cytokines such as TNF-α, IL-6, and chemotactic factors (e.g., CCL5 and CCL8)." (PMID 29765984, 2018). "In addition, findings from IL-6-deficient mice, which develop mature-onset obesity, demonstrated a suppressive effect of IL-6 on the development of obesity." (PMID 30374329, 2018). "Increased IL-6 levels have been reported in obesity in both humans and rodents." (PMID 29868016, 2018). "Classic conditions associated with inflammation including IL-6 levels in plasma, NFκB activation, or obesity were similar in participants with and without MMD in our study." (PMID 29531242, 2018). "In addition, in this 3D model, the expression of TNFα was increased, in case of obesity, and a positive correlation was highlighted between genes coding for inflammatory proteins such as IL-6 and TNFα." (PMID 29389973, 2018).
Obesity (continued). "It has been suggested that obesity-related inflammatory cytokines, including tumor necrosis factor α (TNFα), interleukin-1β (IL-1β) and IL-6, may accelerate muscle catabolism." (PMID 29949600, 2018). "Besides leptin, other obesity-related metabolites, like adiponectin or IL-6, are shown to influence NK cell functionality." (PMID 29560551, 2018). "The adverse impact of obesity upon the periodontium could be mediated by proinflammatory cytokines such as interleukins (IL-1, IL-6 and TNF-α), and an inverse relationship has been reported with antioxidants." (PMID 29680852, 2018). "Furthermore, obesity has been regarded as a condition of chronic low-grade inflammation with elevation of pro-inflammatory cytokines, including tumor necrosis factor and interleukin-6." (PMID 29288474, 2018). "Recently, obesity has been characterized by a low-grade inflammatory state known as inflammome, indicated by chronic increases in circulating concentrations of inflammatory markers, including pro-inflammatory cytokines (e.g., IL-6 and TNF-α) and protein C." (PMID 29497960, 2018). "IL-6 is increased in diabetes, obesity, and various cancers." (PMID 30591653, 2018). "Obesity and T2DM are associated with a low chronic subclinical inflammatory state, which is mediated by inflammatory mediators (e.g., TNFα, IL-6, iNOS, and C-reactive protein) produced by adipose tissue, macrophage infiltration, and insulin insensitivity in adipose tissue." (PMID 30356719, 2018). "For example, obesity induced by high-fat, high-sugar diet (HFSD) is associated with prolonged elevation of proinflammatory serum markers such as IL-6 and inflammation in peripheral tissues, as well as metabolic dysregulation, including insulin and leptin resistance." (PMID 30348225, 2018). "Like TNFα, the levels of IL-6 in plasma increase with fat mass and obesity." (PMID 30366378, 2018). "However, the magnitude of reduction is less pronounced in WT mice, thereby suggesting that IL-6 partially protects against suppressed expression of PGC-1α induced by obesity." (PMID 30134607, 2018). "Indeed, many reports have demonstrated the linkage between the increased production of inflammatory cytokines, such as TNF-α, IL-6 and certain adipokines, during the inflammatory process in obesity and the development of insulin resistance." (PMID 30914847, 2018). "Above all, previous studies have shown that KLF7 may closely relate to IL-6 overexpression induced by high levels of free fatty acids in obesity." (PMID 30598636, 2018). "This suggests that induction of IL-6 could be a common mechanism shared between obesity-induced and IBD-induced disease progression." (PMID 29695802, 2018). "Activation of TLR4 by saturated fatty acids elicits, through the activation of NFκB, the secretion of several proinflammatory cytokines such as TNF-α, IL-6, and MCP-1, which are involved in the development of obesity-associated inflammation and insulin resistance." (PMID 30116154, 2018). "However, TNFα and IL-6 not only impact systemic insulin sensitivity in obesity, but also promote cancer, since these cytokines are also produced from cells of the tumor microenvironment." (PMID 30591653, 2018). "In all-cause dementia negative correlation of adiponectin with obesity, glucose metabolism parameters, IL-6 and hsCRP and positive correlation with HDL-cholesterol were found." (PMID 28421328, 2017). "Similarly to PS, subclinical inflammation induced by obesity is characterized by increased production of inflammatory cytokines IL-6 and TNF-α and higher C-reactive protein (CRP) levels." (PMID 28947858, 2017). "Also measures of obesity, such as BMI, are also known to correlate with peripheral IL-6 concentrations." (PMID 29358917, 2017).